TIE1 (tyrosine kinase with immunoglobulin like and EGF like domains 1)
Diseases named in the same sentence as TIE1 in open-access papers (continued):
Sharing a sentence is not in itself a finding about the gene and the disease.
tumor (continued). "Knockdown of Basigin or treatment with the Basigin inhibitor AC-73 reversed the tumor-promoting effect of TIE1 in vitro and in vivo." (PMID 38617545, 2024). "Specifically, we observed that TIE1 promotes tumor progression by upregulating immunosuppressive cells such as M2 while downregulating mast cell expression." (PMID 38706903, 2024). "It is known that TIE1 is upregulated in tumor vessels, thus contributing to tumor progression, but its roles in tumor cells have been rarely explored." (PMID 36814284, 2023). "MXRA8 appears to regulate these processes by altering genes like ADAMTS1 and TIE1 that influence the tumor microenvironment." (PMID 37762032, 2023). "Downregulation of Tie-1 expression in ECs can inhibit tumor growth, and Tie-1 depletion can improve the anti-tumor angiogenesis effect of Ang/Tie-2 targeted therapy." (PMID 34975347, 2021). "A new function-blocking antibody targeting the endothelial orphan receptor Tie1 (AB-Tie1-39) specifically suppresses tumor cell extravasation at secondary sites when applied in neoadjuvant or peri-operative settings, but is ineffective as adjuvant therapy." (PMID 33671981, 2021). "A few studies have demonstrated that Tie-1 is highly expressed in tumor cells in some cases of invasive ductal carcinoma of the breast, and is positively associated with the rate of lymph node metastasis." (PMID 34975347, 2021). "In tumor angiogenesis, the deletion of the Tie-1 gene in ECs was found to inhibit the phosphorylation level at Tie-2 y1106 and reduce the migration ability of ECs." (PMID 34975347, 2021). "In colorectal adenocarcinoma cells, Tie-1 expression is positively correlated with depth of invasion, tumor stage, and lymph node metastasis." (PMID 34975347, 2021). "Immunohistochemical staining of the cell division marker Ki67 in xenograft tumor tissues confirmed that cells become more sensitive to cisplatin and cell division is reduced when the expression of Tie1 is lowered." (PMID 33461544, 2021). "Tie1 knockdown was found to enhance the anti-tumor effect of cisplatin in vivo as demonstrated by the reduced volume of tumors." (PMID 33461544, 2021). "The mechanisms of action mediating the effects of Tie-1 in tumor growth and progression are currently a hot topic in the medical research community." (PMID 34975347, 2021). "Based on this point of view, our findings suggest that dual therapy likely reinforces the TVN effect by inhibiting Tie1 expression in ECs and tumor cells." (PMID 32641990, 2020). "In a tumor context, Tie1 deletion affects intravasation of tumor cells at the primary tumor site and extravasation of metastasizing tumor cells at secondary sites, resulting in strongly reduced metastatic growth in Tie1iECKO mice." (PMID 32302470, 2020). "Increasing evidence elucidates the role of TIE1 in angiogenesis and its implications on tumor progression." (PMID 33217955, 2020). "Tie1 upregulation in the tumor vasculature has been known for over 25 years but has only recently been investigated as a potential therapeutic target." (PMID 32406209, 2020). "When the number of cancer stem cells in tumour tissues is decreased and Tie1 expression is reduced, cell division and angiogenesis rates will decrease." (PMID 32174801, 2020). "For example, Tie1 deletion prevented extravasation of tumor cells into the lungs and reduced metastatic foci by inhibiting angiogenesis and vascular abnormalization in experimental murine metastasis models." (PMID 31974361, 2020). "Induced postnatal EC deletion of Tie1 in mice results in impaired primary tumor growth due to vascular defects and also leads to reduced metastasis due to inhibition of tumor cell extravasation." (PMID 32406209, 2020). "In fact, the difference in the CLEC14A/TIE1 ratio alone was significant enough to allow the correct identification of sample status (healthy or tumour) in almost 75% of samples." (PMID 32696621, 2020).
tumor (continued). "Tie1 is essential for vascular development and functionally involved in tumor angiogenesis independent on VEGF signaling 45-47." (PMID 32641990, 2020). "High baseline plasma Tie1 level is a promising prognostic marker for both poor progression-free survival and for poor overall survival in metastatic breast patients treated with bevacizumab-taxane combination." (PMID 31340773, 2019). "In this study, to elucidate Tie1 expression patterns and to obtain insight into its physiological functions in tumors, we performed immunohistological analyses in a tumor‐bearing mouse model." (PMID 28464467, 2017). "Using this cell line, we performed immunohistochemistry for Tie1 on tumor tissue dissected from the mouse tumor‐bearing mouse." (PMID 28464467, 2017). "This suggests that Tie1 expression is likely to be induced by combined effects of several components of the tumor microenvironment." (PMID 28464467, 2017). "Quantitative RT‐PCR analysis revealed that the expression of Tie1 in 5‐FU‐treated tumor cells was higher than in control cells." (PMID 28464467, 2017). "Ang2 blocking biologicals and the genetic deletion of Tie1 decreased tumour angiogenesis and tumour growth by reducing tumour cell proliferation and EC sprouting and by inducing vessel regression and EC apoptosis." (PMID 27941161, 2017). "Further analysis using sphere‐formation culture revealed that Tie1‐positive cells are enriched within the population of tumor cells with cancer stemness properties." (PMID 28464467, 2017). "Blocking of ANGPT2 protein or genetic deletion of TIE1 has been shown to decrease tumor angiogenesis and growth by reducing endothelial cell sprouting and by inducing endothelial cell apoptosis and vessel regression." (PMID 29017512, 2017). "This suggests that Tie1 expression can only be maintained in vivo, and needs to be induced in the specific microenvironment of the tumor." (PMID 28464467, 2017). "Tie1 is expressed in the vasculature of human tumours and conditional Tie deletion was demonstrated to inhibit tumour growth and neovascularization." (PMID 27941161, 2017). "Taking these data together, we conclude that Tie1 expression is positively correlated with cancer stemness properties of malignant tumor cells." (PMID 28464467, 2017). "More recently, conditional EC-specific Tie1 deletion was shown to inhibit tumor growth and angiogenesis as well as retinal neovascularization." (PMID 26436659, 2015). "In line with our previous findings, tumor size in pSico-Con treated β3-null/Tie1-Cre+ mice was greater than similarly treated wild-type/Tie1-Cre+ mice." (PMID 20339539, 2010). "Taken together, these data indicate that, while no biological effect of Rac-1 knockdown was observed in wild-type/Tie1-Cre+, the lentivirus treatment efficiently reduced expression of Rac1 in tumor blood vessels from these animals." (PMID 20339539, 2010). "Our results demonstrated that expression of seven alternative splice variant mRNAs (VEGFR1, VEGFR3, Met, RAGE, Tie1, FGFR1, and Kit) is present in multiple normal and tumor tissues." (PMID 18593464, 2008). "The expression profile of TIE1 exhibits considerable heterogeneity across various tumor types." (PMID 38706903, 2024). "All these results indicate a potential mechanistic pathway through which TIE1 may promote tumor progression." (PMID 38706903, 2024). "However, AC-73 treatment attenuated the enhanced MVD induced by TIE1 overexpression, suggesting that TIE1 promoted xenograft tumor angiogenesis through Basigin in vivo." (PMID 38617545, 2024). "Our analysis revealed a robust negative association between tumor purity and TIE1 (r = -0.164 p = 1.33e-03), which was consistent with findings from TISIDB." (PMID 38706903, 2024). "Therefore, in the hypoxic tumor microenvironment, genes that are involved in mechanisms related to stemness and drug resistance, such as Tie1 and KLF5, are artificially upregulated." (PMID 33461544, 2021).
tumor (continued). "Additionally, previous research has found that Tie-1 deletion in experimental murine metastasis models prevents extravasation of tumor cells into the lungs and reduces metastatic foci." (PMID 34975347, 2021). "In contrast to the well‐understood Ang1/Ang2/Tie2 signaling axis, the functional role of the second Tie receptor, Tie1, during tumor progression and metastasis, remains elusive, which may mechanistically be largely due to its orphan receptor status." (PMID 32302470, 2020). "Whether Tie1 is expressed on other cell types within the tumor microenvironment and what effects the antibody would have on such cells will also need to be investigated." (PMID 32406209, 2020). "This raises the question of whether dual therapy affects Tie1 expression in ECs as well as tumor cells." (PMID 32641990, 2020). "The possible synergistic effect of dual inhibition of Tie1 and Ang2 might be due to Ang2 influencing earlier phase in tumor growth than Tie1." (PMID 31340773, 2019). "Although Tie1 expression in endothelial cells is increased in tumor vessels and deletion of the Tie1 gene in tumor-bearing mice decreased tumor growth and angiogenesis in preclinical experiments, the significance of Tie1 in tumor progression is also unclear." (PMID 31340773, 2019). "Because Tie1‐positive cells were observed in the in vivo tumor and the in vitro sphere‐formation model, we investigated whether Tie1 expression is accompanied by the expression of cancer stem cell marker genes in vivo." (PMID 28464467, 2017). "In our studies, it was difficult to assess the tumorigenic ability of Tie1‐positive HT29 cells sorted from tumor‐bearing mice because of the extremely low number of such cells that we could acquire." (PMID 28464467, 2017). "Moreover, enhancement of cancer stemness properties by exposure to an anticancer drug resulted in increased Tie1 expression in tumor tissue." (PMID 28464467, 2017). "We further determined that Tie1‐positive tumor cells could be cultured in vitro using sphere formation, a condition enriching cancer stem cell (CSC) populations." (PMID 28464467, 2017). "It is noteworthy that Tie1 was not required under basal conditions in adult mice, but its deficiency resulted in decreased survival of ECs in the tumour vasculature." (PMID 27941161, 2017). "To confirm whether Tie1 expression increased on treatment of HT29 tumor‐bearing mice with anticancer drugs, we assessed its expression by tumor cells collected from mice treated or not treated with the drug 5‐FU." (PMID 28464467, 2017). "We selected these genes because all six were present in the angiogenesis signature unique to PDAC, because CYP1B1 was the most significantly and highly up-regulated, and because ANGPT1, its receptors TIE1 and TEK, and HIF1A are commonly associated with pathways that enhance tumor angiogenesis." (PMID 26586478, 2016). "In contrast, analysis of tumors grown in wild-type/Tie1-Cre+ mice showed a loss of GFP expression in endothelial cells but not tumor cells, indicating that endothelial-specific Cre-recombination was efficient." (PMID 20339539, 2010). "Furthermore, the research on the tumor microenvironment (TME) and tumor purity also proved that TIE1 may be an oncogene." (PMID 38706903, 2024). "Indeed, the Tie1‐specific antibody AB‐Tie1‐39 (which activates Tie2 in vivo) could protect mice from lung metastases when used in a neoadjuvant treatment setting before primary tumor resection." (PMID 34125494, 2021). "Thus, it will be important to determine whether the appearance of a very small population of CSCs expressing Tie1 protein can explain the increase in Tie1 at the mRNA level in whole tumor tissue." (PMID 28464467, 2017). "The Roselyne Tournaire group reported in 2012 and 2021 that decreased TIE1 and TNF-α signaling can induce EndMT in endothelial cells and contribute to tumor stroma formation, particularly CAF accumulation." (PMID 41154806, 2025).
tumor (continued). "Angiopoietins, including ANGPT1, ANGPT2, and ANGPT4, have been reported to act as ligands of the tyrosine kinase receptors TIE1 and TIE2 to activate MAPK signaling pathways during tumor angiogenesis in mammals." (PMID 37155312, 2023). "Simultaneous infection of stromal and tumor cells; Upregulation of Fez1 and Pycard; Downregulation of DLL-4, Angiopoietin 2, PECAM, Tie-1, and FOS EGR2, CREB-5, IL-6, Map2K1, CCL22, TIMD4 and CCL19." (PMID 35640930, 2022). "Angiopoietins (Ang1 and Ang2) and their RTK (TIE1 and TIE2) are key mediators of tumor angiogenesis." (PMID 33918704, 2021). "However, research on the expression of Tie-1 in tumors and its association with the clinicopathological characteristics and prognosis of tumor patients, as well as the mechanisms mediating its role in tumor progression, have not been well studied." (PMID 34975347, 2021). "The results indicated that the expression of tumor cell-derived VEGFA, IGFBP3, EFNA1, EFNB1, IGF2, PDGFA and stroma-derived Angpt2, Cdh5, Esam, Esm1, Icam2, and Tie1 was statistically correlated with that of Pecam1 and elevated in p-EMT TW2.6 tumors." (PMID 34869001, 2021). "Western blotting further determined that dual therapy effectively inhibited Tie1 expression not only in ECs but in tumor cells compared with BEV monotherapy, confirming that dual therapy downregulates the Tie1 expression." (PMID 32641990, 2020). "Among the candidate list we identified (MMP10, IL1α, TIE1, FGF2, BMP6), IL1α has been reported to be released by both stromal cells and PC cells, and to promote tumor growth in PDAC." (PMID 33105540, 2020). "Tumour growth was further reduced by the soluble Tie2 ectodomain, but anti-VEGF therapy in the Tie1-deleted mice." (PMID 27941161, 2017). "Detailed analysis using tumor‐bearing models and immunohistochemistry combined with Flow cytometric analysis and cell sorting (FACS) revealed that Tie1 protein was expressed in a small population of malignant tumor cells." (PMID 28464467, 2017). "In wild-type/Tie1-Cre− mice, GFP expression was detected in both the tumor cells and the majority of endothelial cells lining blood vessels, indicating a high efficiency of lentiviral infection in vivo." (PMID 20339539, 2010). "While TIE1 knockdown did not alter in vitro growth, it significantly suppressed tumor growth in vivo." (PMID 41235901, 2025). "Together, these results indicate that TIE1 promotes primary tumor growth but does not contribute to lung metastasis, suggesting its role in breast‐cancer progression is specific to primary tumor growth." (PMID 41235901, 2025). "The mouse tumor model lacking TIE1 reduces tumor angiogenesis and normalizes blood vessels, resulting in increased tumor necrosis and ultimately postponed tumor development." (PMID 38706903, 2024). "Therefore, we employed ESTIMATE analysis to evaluate the relationship between TIE1 expression and TME score to assess the impact of TIE1 on TME and its influence on tumor prognosis." (PMID 38706903, 2024). "This current study is the first description of a human antibody against Tie1 with the potential for clinical use in targeting extravasation of tumor cells into organs such as the lung, without having a detrimental effect on immune cell infiltration." (PMID 32406209, 2020). "The experiment results showed that the number of tumour stem cells (proportion of CD44+/CD133+ cells) and Tie1-positive cells in tumours originating from miR-485-5p@SPIONs-HuGSCs was significantly lower than that in those originating from miR-mut@SPIONs-HuGSCs." (PMID 32174801, 2020). "CLEC14A expression in tumour tissues (normalised to PECAM1 or TIE1 expression) is also significantly above most, but not all, non‐tumour pathologies." (PMID 32696621, 2020).
tumor (continued). "K. Khan and R. Kerbel highlight the first description of a human antibody against Tie1 with the potential for clinical use in targeting extravasation of tumor cells into organs such as the lung, without having a detrimental effect on immune cell infiltration." (PMID 32406209, 2020). "Notably, dual therapy inhibited Tie1 expression, the key regulator of TVN, in both endothelial cells and tumor cells." (PMID 32641990, 2020). "In tumours, however, high CLEC14A/TIE1 ratios indicate that CLEC14A mRNA levels are significantly higher in endothelial cells than could be expected based on shear stress alone." (PMID 32696621, 2020). "While the roles of both Tie-1 and Tie-2 in AGASACA and TC are currently unknown, further investigation is warranted given the observed phosphorylation of both receptors in many tumor samples in this study." (PMID 22630170, 2012). "Immune infiltration analysis suggested that TIE1 is positively correlated with macrophages M2 and negatively correlated with Mast cells, naive B cells and Follicular helper T cells (TFH), which may be a contributing factor to tumor progression." (PMID 38706903, 2024). "This suggests that blocking of Tie1 using this antibody may be detrimental during developmental but not tumor angiogenesis, unlike genetic deletion of Tie1 in ECs, both of which are impaired." (PMID 32406209, 2020). "Interestingly, we found that only a small population of tumor cells expressed the Tie1 protein and that it was not maintained under normal 2D cell culture conditions." (PMID 28464467, 2017). "Additionally, only TIE1 amplification—not TIE2—is associated with poor prognosis in breast‐cancer patients, reinforcing the idea that TIE1 may contribute to tumor progression in a TIE2‐independent manner." (PMID 41235901, 2025). "Interestingly although this elevated expression was indicated from transcript analysis using CLEC14A/PECAM1 ratios, it was not from CLEC14A/TIE1 ratios, implying that in this tumour elevated CLEC14A expression may be more a result of reduced flow rates." (PMID 32696621, 2020). "Thus, we could not directly compare the behaviors of Tie1‐positive cells with Tie1‐negative cells from tumor‐bearing mice in terms of their migratory abilities, matrix digestion, sphere formation, and other properties." (PMID 28464467, 2017). "Because none of these colocalized with the Tie1 signal, we conclude that the Tie1‐positive cells indeed originated from the injected HT29‐EGFP tumor cells, and not from any murine cells." (PMID 28464467, 2017).